CCL22 (C-C motif chemokine ligand 22)
Diseases named in the same sentence as CCL22 in open-access papers (continued):
Sharing a sentence is not in itself a finding about the gene and the disease.
undifferentiated carcinoma (1 paper, 2015). A usually aggressive malignant epithelial neoplasm composed of atypical cells which do not display evidence of glandular, squamous, or transitional cell differentiation. "Women with endometrioid cystadenocarcinoma had significantly higher (p < 0.05) PF CCL22 levels than patients with undifferentiated carcinoma." (PMID 25647263, 2015). "Women with endometrioid cystadenocarcinoma had higher PF CCL22 levels than women with undifferentiated carcinoma." (PMID 25647263, 2015).
uveitis (1 paper, 2015). An inflammatory process affecting a part of or the entire uvea. "Production of S100B during uveitis either by resident cells in the eye or by infiltrating cells is therefore likely to have up-regulated CCL22 and IL-1β in particular resulting in further recruitment of inflammatory cells and exacerbation of disease." (PMID 26204512, 2015).
viral meningitis (1 paper, 2019). Inflammation of the membranes surrounding the brain and spinal cord due to a viral infection. "A significant increase of CCL22 concentrations was observed in CIS-RRMS and viral meningitis." (PMID 31727097, 2019).
Whipple disease (1 paper, 2010). A systemic infection caused by the Gram-positive bacterium Tropheryma whipplei. "Arginase, the M2 chemokines Ccl22 and Ccl17, and the IL-1 receptor antagonist were induced in macrophage following infection as it has been described in Whipple's disease lesions." (PMID 20090833, 2010).
tumor (560 papers, 2008 to 2026). "In the tumor microenvironment, CCL22 has been implicated in recruiting Tregs, which can suppress antitumor immune response and contribute to immune evasion." (PMID 41295982, 2026). "CCL22 plays a critical role in maintaining immune homeostasis, promoting anti-inflammatory responses, and has been implicated in tumor immune evasion and transplant tolerance by facilitating Treg accumulation." (PMID 40894040, 2025). "The recruitment of Tregs to the tumor site is driven by the chemokine C-C motif chemokine ligand 22 (CCL22; encoded by CCL22), which is secreted by tumor-associated macrophages and tumor cells." (PMID 41550427, 2025). "In BC lymphocyte recruitment, CCL17/CCL22 acts as a ligand for CCR4, and CCL17/CCL22 is closely associated with Foxp3+ tumor-infiltrating regulatory T cells (Ti-Tregs)." (PMID 39329710, 2024). "In the context of cancer, CCL22 has been implicated in promoting tumor progression and immune evasion." (PMID 38928238, 2024). "Predominantly anti‐inflammatory markers, such as CD206, IL‐10, IL‐8, CCL8, and CCL22 are known to be associated with advanced tumor stage and poor survival." (PMID 38037545, 2023). "Proinflammatory CD80, anti‐inflammatory CD206, CCL18, and CCL22, and the tumor‐associated markers including MMPs, MGLL, and TLR4 were expressed by a low proportion of monocytes (<1%), but significantly upregulated in TAM." (PMID 38037545, 2023). "Tumor cells and tumor-associated macrophages secrete the chemokines CCL22 and CCL17, which attract CCR4+ Treg cells." (PMID 37107673, 2023). "Tumor‐associated macrophages (TAMs)‐released C‐C motif chemokine 22 (CCL22) can activate intratumoral focal adhesion kinase (FAK), thus promoting the progression of ESCC." (PMID 37846367, 2023). "We also found that several of the downregulated genes including Ccl1, Ccl22, Cxcl13 or Ccr7 were associated with immunosuppression and decreased anti-tumour immunity." (PMID 37516803, 2023). "M2 macrophages or tumor-associated macrophages (TAMs) secrete CCL22 and draw Tregs and MDSCs into the TME strengthening an immunosuppressive milieu." (PMID 38264664, 2023). "Expression of several other genes upregulated by ruxolitinib such as Csf2, Cx3cl1, Cx3cr1, Has1, and Ccl22 in myeloid cell populations is known to be associated with tumor progression, myeloid cell accumulation, and tumor progression." (PMID 37005447, 2023). "Treg cells express CC chemokine receptor 4 (CCR4), the receptors of CC chemokine ligand 22 (CCL22), and can migrate to CCL22 derived from tumor cells and tumor associated macrophages in the TME, thus realizing the recruitment of Treg cells." (PMID 36908706, 2023). "In our experiments, we discovered that only M2 macrophages (tumor-associated macrophages) present in the TME express higher levels of CCL22/CCL17 than other macrophage subsets." (PMID 35222362, 2022). "In the TME, the core tumor cells as well as tumor-associated macrophages secrete high amounts of CCL22/CCL17." (PMID 35222362, 2022). "Primary tumor cells and tumor-associated macrophages (TAMs) from ovarian tumors produced CCL22, a ligand for CCR4, which was crucial for the migration Tregs, whose CCR4 expression was higher than other CD4+ T cells." (PMID 33603130, 2022). "For example, tumor cells and tumor-associated macrophages secrete CCL22 facilitate Tregs accumulated." (PMID 35935577, 2022). "The C-C motif chemokine ligands, CCL17, CCL18, and CCL22, which are secreted from activated TAMs, are associated with the enlargement of tumor size and the promotion of tumor metastasis, and the recruitment of Treg cells." (PMID 35955737, 2022). "CCL22 is one of the several Cys-Cys (CC) cytokine genes, mainly produced by M2-like tumor-associated macrophages in the tumor microenvironment." (PMID 35480305, 2022).
tumor (continued). "Rather, thrombin stimulation resulted in macrophages adopting a pro-resolving phenotype characterized by the secretion of CCL22, a cytokine most akin to M2 and tumor-associated macrophages that impacted expression of genes of the TGF-β pathway." (PMID 35626753, 2022). "We found that Mettl3-deficient TAMs expressing relatively high levels of CCL22 were responsible for Treg recruitment within the complex tumour microenvironment." (PMID 33654093, 2021). "In ovarian cancer, tumor cell- and TAM-derived CCL22 contributed to tumor growth via stimulation of Treg tumor infiltration, which was associated with reduced survival through suppression of tumor-specific T cell immunity." (PMID 34503058, 2021). "Several essential cytokines were also higher in the high-risk group, such as CCL5 (recruiting MDSC to tumor site), CCL22 (driving Treg recruitment into tumor site), and IL-10 (inhibiting cytokine synthesis)." (PMID 34961815, 2021). "It has also been shown that CCR4-expressing Treg cells are recruited into tumor tissues by CCL22 that is produced in the tumor microenvironment by tumor cells and tumor-associated macrophages." (PMID 34771703, 2021). "In EBV‐associated GC, the enhanced CCL22 produced by EBV+ tumor cells promoted the accumulation of Tregs." (PMID 32573058, 2020). "We showed that Etanercept reduces the transcript levels of TNF-α, IL10 and CCL22, all of which are associated with tumor progression." (PMID 32883235, 2020). "Due to the recruitment of cancer-related cells in the squamous cell carcinoma of the tongue into the tumor niche, increased expression of CCL22 is associated with a poorer prognosis." (PMID 33182504, 2020). "Our findings suggest that the clinical benefits of bexarotene are partially attributable to suppressive effects on the production of CCL22 by M2-polarized tumor-associated macrophages." (PMID 31616630, 2019). "IL-1B has been linked with poor prognosis in breast cancer, whereas tumour-induced IL-1A has been linked to CCL22 production by tumour-infiltrating immune cells." (PMID 29760166, 2018). "Treg cells reach the tumor lesions by sensing CCL22, mainly produced by tumor associated macrophages (TAMs) and cancer cells, and CCL28, found in tumor hypoxic regions." (PMID 30591657, 2018). "Skin-homing T cells CC-chemokine receptor 4 (CCR4) binds to CCL22 (macrophage-derived chemokine) expressed by tumor-associated macrophages (TAM) and are recruited to the tumor site." (PMID 32309563, 2015). "CCL22, secreted by the tumor cells causes accumulation of CCR4+ T-regulatory cells at tumor site resulting in immune suppression." (PMID 24384839, 2013). "The observed effects on cell migratory properties have been attributed to treatment-associated increases chemokine (C-C motif) ligand 22 (CCL22) levels in the tumor cell supernatants." (PMID 23378947, 2013). "In the tumor microenvironment (TME), the dualistic nature of chemokines was highlighted: tumor-associated macrophages (TAMs) could secrete immunosuppressive factors, such as CCL22 and CCL5, recruiting inhibitory cells and inducing CD8+ T cell exhaustion." (PMID 41635851, 2026). "Accumulation of Tregs is driven by the chemokine C-C motif chemokine 22 (CCL22) produced predominantly by the tumor, as well as by tumor-associated macrophages and dendritic cells in the TME via interaction with its counter receptor, chemokine receptor 4 (CCR4), expressed on Tregs." (PMID 41303751, 2025). "Moreover, the limited availability of tumor tissue samples precluded further investigation into the association between CCL22 and CCR4 expression and tumor metastasis." (PMID 39513112, 2024). "In OC, TAMs are predominantly M2 macrophages that produce and secrete anti-inflammatory/immunosuppressive cytokines such as IL-10 and transforming growth factor beta 1(TGFB1) and chemokines (CCL17, CCL18, and CCL22) associated with tumor invasion, angiogenesis, metastasis, and early recurrence." (PMID 37298230, 2023).
tumor (continued). "The encoded chemokine CCL22 mediates the trafficking of regulatory T cells to the tumor, by which tumors may foster immune privilege." (PMID 37483625, 2023). "This is consistent with the reduced expression of many of the known genes that contribute to M-MDSC-suppressive function as identified in our scRNAseq dataset, including S100a8, S100a9, Ccl22 and Bcl2a1a which decreased in tumor M-MDSCs in ILC2-deficient settings." (PMID 35658010, 2022). "Here, we showed that tumor-associated macrophages (TAMs) produced an abundance of C-C motif chemokine 22 (CCL22), whose expression in the tumor stroma was positively associated with the level of intratumoral phospho-focal adhesion kinase (pFAK Tyr397), tumor metastasis and reduced patient survival." (PMID 35962191, 2022). "Additionally, tumor-associated macrophages (TAMs) and tumor cells in OC secrete high levels of CCL22 which is a Treg recruiting chemokine." (PMID 36011029, 2022). "Additionally, the secretion of CXCL2 and CCL22 by the isoform Np63-carrying BC cells has been reported to be associated with MDSC migration to the primary tumor and metastatic sites in TNBC." (PMID 34885122, 2021). "CCL22 has been implicated in the recruitment of CCR4+ Tregs from peripheral blood to tumor tissues." (PMID 33710805, 2021). "The mechanisms by which growing tumors can stimulate Treg lymphocyte proliferation and differentiation are not well known, but the production of prostaglandin E2 by tumor cells and the cytokine CCL22 by tumor-associated macrophages can act as chemotactic and differentiation agents for these cells." (PMID 32878124, 2020). "In addition, cancer cells and tumor-infiltrating macrophages express CCL22, which causes Treg migration into the tumor tissue, and suppression of an anti-tumor immune response, leading to worse prognosis and increased risk of metastasis." (PMID 32179746, 2020). "Disseminated disease (stages III and IV) were characterized by high amounts of Tregs, tumor-associated macrophages (TAMs), DCs, and high levels of CCL22, which is secreted by tumor cells, TAMs and DCs to enable further recruitment of Tregs and immunosuppression." (PMID 30042343, 2018). "The predominant chemokine receptor on human Treg is CCR4, the receptor for the chemokines CCL17 and CCL22, which are produced by tumor cells, tumor- associated macrophages and dendritic cells, as well as by effector T cells (Teff) in the setting of an inflammatory anti-tumor response." (PMID 30400822, 2018). "Notably, in one recent study of 417 cases of invasive breast cancer, high tumor expression of CCL22 was associated with higher histological grade and greater density of tumor-infiltrating Tregs." (PMID 26217588, 2015). "Interestingly, a similar association was identified at current study between tumor-derived CCL22 expression and the molecular subtypes of BC." (PMID 24124553, 2013). "Factors that are known to promote SCC progression and have been associated with poor prognosis included CCL22, a chemokine that attracts regulatory T cells (Tregs) that shut down the anti-tumor immune response, IL-10, an immuno-regulatory/suppressive cytokine, and IL-4, a prototypical Th2 cytokine." (PMID 22558071, 2012). "Tregs may be recruits to the tumor site by the chemokine CCL22 produced by the tumor cells and tumor-associated macrophages (TAMs)." (PMID 22190975, 2011). "Previously, we have utilized MDC/CCL22 to induce a Th2-type immune response to DNA vaccine encoding tumor or viral antigens and generated high titers of therapeutic antibody, suggesting that this may also enable us to develop a safe and potent AD vaccine." (PMID 18461171, 2008). "Considering the strong linear correlation of CCL22 between S/M and tumor cells, with higher levels in tumor cells and diffuse staining of the stroma, the possible causes include a mutual stimulation of the cell types and a chemokine uptake by tumor cells from the surrounding stroma." (PMID 39232378, 2024).
tumor (continued). "Although these data provide important proof of concept that therapeutically activating CCL22 could be effective and feasible, we are well aware that CCL22 is elevated in the tumor tissues, which is linked to Treg recruitment and contributes to an immunosuppressive environment for tumors." (PMID 38924414, 2024). "Moreover, CCL22 expression was found to be associated with the tumor histological features known to be related with unfavorable prognosis of patients, including high histological grade (P<0.0001), negative ER (P<0.0001), negative PR (P=0.001), and HER2 amplification (P=0.028)." (PMID 24124553, 2013). "Hypoxia-induced CCL28 and CCL22 recruit Treg cells in tumor and ascites, thereby promoting immune privilege, in turn, sustaining cancer cell growth." (PMID 40369674, 2025). "Our findings suggested that CCL2 and CCL22 from ZEB1-expressing alveolar macrophages increase CTL abundance to limit metastatic lung colonization of KPC tumor cells." (PMID 40595293, 2025). "Tumor cells and stromal cells recruit Tregs to the tumor site primarily by secreting chemokines such as CCL22, CCL17 (binding to CCR4 on Tregs), and CCL28 (binding to CCR10)." (PMID 40698080, 2025). "In HNSCC, for instance, senescent tumor cells secrete elevated amounts of TGF-β and CCL22, promoting the infiltration of Tregs and impairing the ability of effector T cells to mount an effective anti-tumor response." (PMID 41463272, 2025). "Through the secretion of chemokines such as CCL22, TAMs recruit Tregs or suppressive T cells, while ligand–receptor interactions with tumor cells further reinforce the immunosuppressive network." (PMID 41562080, 2025). "Tumour-secreted IL-1 can trigger dendritic-cell CCL22 release, an effect blocked by an IL-1 receptor antagonist." (PMID 41291326, 2025). "The FOXO3/CCL22 pathway mediates the recruitment of regulatory T cells (Tregs) into the tumor microenvironment by regulating the expression of the chemokine CCL22, thereby promoting tumor immune escape." (PMID 41231037, 2025). "For instance, MDSCs secrete chemokine ligand 22 (CCL22), which recruits Tregs to the tumor microenvironment by binding to chemokine receptor 4 (CCR4) on Treg surfaces." (PMID 41488631, 2025). "CCL22 facilitates tumour progression and immune evasion by recruiting Tregs, thereby establishing an immunosuppressive TME." (PMID 40361472, 2025). "Previous studies have shown that CCR4, binding with CCL17/CCL22, can induce Treg cell enrichment within the tumour microenvironment (TME)." (PMID 40000397, 2025). "In vitro migration assays further demonstrate that CCL17, CCL20, and CCL22 exert chemotactic effects on tumor-derived Th17 cells." (PMID 40134607, 2025). "CCL22, produced by both tumour and immune cells, primarily binds to CCR4, which is expressed on Tregs, Th2-polarised T-cells, and specific DC subsets." (PMID 40361472, 2025). "IL-1α, secreted by cancer cells, has been identified as a driver of CCL22 production, further amplifying Treg recruitment and suppressing anti-tumour immunity." (PMID 40361472, 2025). "GBM tumor cells and associated myeloid populations produce immunomodulatory factors such as indoleamine 2,3-dioxygenase (IDO), CCL2, and CCL22, which contribute to the recruitment and regulation of T cell populations within the tumor microenvironment." (PMID 40867165, 2025). "Tumor cells and tumor-associated macrophages upregulate CCL22 and CCL17, ligands for CCR4, which promote Treg chemotaxis toward the tumor microenvironment." (PMID 41394821, 2025). "In GBM, tumor-derived chemokines such as CCL2 and CCL22 bind to CCR4 on Tregs and have been implicated in their selective recruitment to the tumor." (PMID 40867165, 2025). "CCL22 secreted by TAMs and OC cells attracts regulatory T cells (Tregs) to OC cell clusters, suppressing T cell immunity and enhancing tumor growth." (PMID 40369674, 2025).